Y_RNA (Y RNA )
Gene: Miscellaneous RNA gene on chromosome 11 (108,229,503 to 108,229,604, reverse strand). Ensembl gene ENSG00000206967.
Homologues: Orthologues: chimpanzee Y_RNA (98% identical). Paralogues in human: Y_RNA (94% identical), RNY3 (92% identical), Y_RNA (92% identical), RNY3P1 (91% identical), Y_RNA (91% identical), Y_RNA (90% identical), RNY3P14 (89% identical), Y_RNA (89% identical), RNY3P11 (88% identical), RNY3P16 (88% identical), Y_RNA (88% identical), Y_RNA (87% identical), and 99 more.